PROX1 (prospero homeobox 1)
Diseases named in the same sentence as PROX1 in open-access papers (continued):
Sharing a sentence is not in itself a finding about the gene and the disease.
breast carcinoma (continued). "Moreover, we unraveled a previously unknown action of Prox1 in suppressing the Warburg effect on breast cancer cells that may also apply in other tissues, where Prox1 exhibited tumor-suppressive roles." (PMID 37508533, 2023). "These interactions may also mediate the tumor-inhibiting function of Prox1 in breast cancer cells." (PMID 37508533, 2023). "However, molecular mechanisms behind PROX1 induced breast cancer metastases remain elusive." (PMID 35342346, 2022). "Moreover, PROX1 intervenes ubiquitination of hnRNPK in breast cancer cells." (PMID 35342346, 2022). "Morphological changes indicated that PROX1 may contribute to EMT in breast cancer." (PMID 35342346, 2022). "Thus, this action may participate in Prox1-mediated inhibition of metastasis in breast cancer." (PMID 37508533, 2023). "PROX1 interacts with hnRNPK to inhibit the ubiquitination of hnRNPK, which in turn activates the WNT pathway to promote invasive metastasis of breast cancer." (PMID 37736108, 2023). "The expression of PROX1 were lower in T-47D and MCF-7 breast cancer cell lines, but higher in MDA-MB-231, MDA-MB-468, SUM-159 and BT-549 cell lines." (PMID 35342346, 2022). "It was reported that D2-40 showed higher sensitivity in distinguishing lymphatics than PROX-1 and LYVE-1 in breast cancer tissue." (PMID 35054174, 2021). "In conclusion, these results show that PROX1 acts as a negative regulator of MMP14 expression and MMP14-dependent 3D invasion in multiple cells types, such as BEC and breast cancer cells." (PMID 29934628, 2018). "Among the 340 under-expressed genes containing the 586 hyper-methylated CpGs, there were several tumor suppressor genes with under-expression that has previously been observed in breast cancer, such as L3MBTL4, ID4, RUNX3, PROX1, SFRP1 and others." (PMID 27386846, 2016). "We found that CCR7 mRNA expression in human breast cancer tissues positively correlates with the expression of lymphatic endothelial markers LYVE-1, podoplanin, Prox-1, and vascular endothelial growth factor-C (VEGF-C)." (PMID 25744065, 2015). "It was found that all lymphatic endothelial markers, LYVE-1, Prox1, podoplanin, 5'-nucleotidase and VEGFR-3, were expressed in significantly higher levels in breast cancers than in normal breast tissue." (PMID 18325094, 2008). "A comparison of different endothelial lymphatic markers showed that the sensitivity of D2-40 to recognize intratumoral lymphatic vessels on serial sections of breast carcinomas is higher than that of LYVE-1, podoplanin or Prox-1." (PMID 18307818, 2008). "Additionally, in comparison to Prox-1 and LYVE-1, it is more sensitive in recognizing lymphangiogenesis in breast cancer and displays the strongest immunoreactivity in both intratumoral and peritumoral LECs." (PMID 38549934, 2024). "PROX1 binds to HNRNP K and inhibits its ubiquitination, thereby promoting K protein stability and ultimately activating the HNRNP K-β-Catenin-Wnt axis to promote breast cancer development." (PMID 39366930, 2024). "Similarly, immunostainings of the tumors against antibodies for CD31, VEGF, and OCCLUDIN showed that Prox1 reduced all three markers, indicating a decrease in angiogenesis as well as in the EMT capacity of the breast cancer tumors." (PMID 37508533, 2023). "To further investigate the molecular mechanism that underlies the observed anti-proliferative effect of Prox1, we over-expressed Prox1 in the human cell line MCF7 and we then examined the expression of genes involved in breast cancer hallmarks, including proliferation, metastasis, and metabolism." (PMID 37508533, 2023). "Taken together, these results suggest that Prox1 significantly inhibited the proliferation of breast cancer cells without concurrently promoting cell death." (PMID 37508533, 2023). "Moreover, the interaction of PROX1 and hnRNPK inhibits the ubiquitination of hnRNPK, and subsequently activates WNT pathway to promote the invasion and metastasis of breast cancer." (PMID 35342346, 2022).
breast carcinoma (continued). "In conclusion, PROX1 exerts its pro-metastasis role in breast cancer by interacting with hnRNPK to activate WNT/β-catenin signaling to promote the invasion and metastasis of breast cancer." (PMID 35342346, 2022). "Statistical analysis also showed that the expression of PROX1 was the lowest in Luminal A subtype breast cancer patients without lymph node metastasis, while the expression was highest in triple-negative breast cancer patients with lymph node metastasis." (PMID 35342346, 2022). "Thus, PROX-1 alone is unsuitable as a specific marker for LVD and LVI assessments in breast cancer, but it is really an indispensable marker in identifying mechanisms underlying tumor lymphangiogenesis and origins of LEC when combined with other markers." (PMID 35054174, 2021). "In addition, M-LECPs expressing high levels of LYVE1, PDPN, PROX1 and VEGFR3 were uniquely detected in the lymph vessels of breast cancer tissue and their density correlated with the development of lymphatic metastasis in breast cancer patients." (PMID 33071831, 2020). "ASAP1 has been shown to be necessary for the in vitro invasive potential and in vivo metastatic potential of specific breast cancer cell lines including MDA-MB-231 cells, while increased Prox1 expression promotes the transition of intestinal adenomas to high-grade dysplasia or carcinoma in situ." (PMID 25879659, 2015). "There were differences in the the presence versus the absence and in the circumferential distribution of CD31 and D2-40, Prox-1 and VEGFR-3 immunoreactivities within the normal vessels in the breast cancer sections compared to those vessels containing tumor emboli (p=.01), (p=.01)." (PMID 21297224, 2010). "However, in the context of breast cancer cells, Prox1 is not able to induce p27-KIP1 or other CDKIs, such as p21-CIP1 or p16." (PMID 37508533, 2023). "Moreover, we experimentally demonstrated that Prox1 was sufficient to strongly suppress proliferation, migration, and the Warburg effect in human breast cancer cells without inducing apoptosis." (PMID 37508533, 2023). "Additionally, Prox1 represses PDK1 and induces MPC1 in breast cancer cells." (PMID 37508533, 2023). "Moreover, the existing data are conflicting in terms of the prognostic value of PROX1 in breast cancer and OSCC, while no corresponding reports are available for lung cancer." (PMID 35885529, 2022). "However, the effect of PROX1 on EMT and its influence on the invasion and metastasis of breast cancer remains unclear." (PMID 35342346, 2022). "For example, markers of myeloid lymphatic endothelial cell progenitors (M-LECPs) were found to be expressed on a portion of lymphatic vessels in breast cancer tissue, but not in normal breast tissue, and M-LECPs co-expressed high levels of PROX1, LYVE-1, podoplanin, and VEGFR-3." (PMID 35054174, 2021). "To test this, we chose HuAR2T, an HuVEC cell line, and MDA-MB-321, an invasive breast cancer cell line, both expressing high levels of MMP14, but no PROX1." (PMID 29934628, 2018).
colon cancer (33 papers, 2008 to 2025). "In colon cancer, high PROX1 levels are linked to low E-cadherin levels, and both are associated with LN metastasis and Duke’s stage." (PMID 35885529, 2022). "The enforced expression of PROX1 in colon cancer cells caused the downregulation of E-cadherin and integrins, increased metalloproteinase activity and increased invasivity." (PMID 29652830, 2018). "High PROX1 expression is associated with a poor grade of tumour differentiation, and, in colon cancer patients, also with less favourable patient outcome." (PMID 21970873, 2011). "The association between high PROX1 and poor outcome was further strengthened in female colon cancer patients (CCSS 38% vs 63% P=0.007; RR 2.02)." (PMID 21970873, 2011). "The present results indicate that high PROX1 expression is associated with the high grade of tumour differentiation and less favourable prognosis in the subgroup of patients with colon cancer." (PMID 21970873, 2011). "In the subgroup of patients with colon cancer, high PROX1 expression was associated with unfavourable survival (RR=1.47; P=0.045)." (PMID 21970873, 2011). "In summary, our results show that high nuclear PROX1 expression is associated with unfavourable outcome in colon cancer patients, and in particular among female colon cancer patients." (PMID 21970873, 2011). "Among colon cancer patients the difference in survival was evident in females and high PROX1 expression was associated with worse outcome." (PMID 21970873, 2011). "In the subgroup of patients with colon cancer, high PROX1 expression was associated with unfavourable colorectal cancer-specific survival (CCSS) as compared with low PROX1 expression (CCSS 47% vs 62% P=0.045; RR 1.47)." (PMID 21970873, 2011). "Inhibition of PROX1 expression caused reduced metastatic potential of colon cancer cells in vivo." (PMID 36207986, 2023). "Moreover, our data show that high PROX1 expression is associated with unfavourable outcomes among the subset of female colon cancer patients." (PMID 21970873, 2011). "To investigate how PROX1 overexpression promoted CSCs properties in colonic neoplasms, we examined the PROX1 regulatory pathway." (PMID 38244581, 2024). "Knockdown of PROX1 in colon cancer cell lines can reduce the expression of VEGF-A and increase the expression of angiostatin, while overexpression of PROX1 can promote tumor cell angiogenesis and lymphangiogenesis, and tumor cell proliferation and migration." (PMID 39328205, 2024). "In colon cancer, PROX1 suppresses the expression of E-cadherin at the transcriptional level through the inhibition of microRNA-9-2." (PMID 39328205, 2024). "PROX1 was found to be overexpressed in 43% of colon cancer tissues, and its upregulation correlated with the downregulation of E-cadherin, advanced tumor staging, and the presence of lymph node metastasis." (PMID 39328205, 2024). "Taken together, these results suggest that PROX1 can recruit EZH2 to the SIRT3 promoter region in colon cancer cells, where EZH2 represses SIRT3 transcription." (PMID 36594098, 2023). "PET/CT analysis showed that PROX1 knockdown significantly suppressed glucose uptake by xenografted colon cancer cells and resulted in a decreased SUVmax." (PMID 36594098, 2023). "The expression level of PROX1 was higher in HCT116 and SW480 cells than in other colon cancer cells, and these two cell lines were selected for further PROX1 knockdown experiments." (PMID 36594098, 2023). "In colon cancer, PROX1 inhibits the expression of E-cadherin at the transcriptional level by inhibiting microRNA-9-2, thereby promoting EMT and invasion and metastasis." (PMID 35342346, 2022). "In line with this study, another group of researchers reported that in cases of colon cancer, PROX1 positivity correlated significantly with tumor size, histologic type, lymphovascular invasion, cancer stage, depth of invasion, and LN metastasis." (PMID 35885529, 2022).
colon cancer (continued). "PROX1 regulates cell adhesion and polarity of colon cancer cells, and promotes invasion of several tumour types." (PMID 36033614, 2022). "It’s been suggested, that Prox1 is a downstream target gene of β-catenin/TCF in colon cancer, and Prox1 can lead to enhanced cell adhesion." (PMID 34183992, 2021). "In fact, it was shown that the homeobox PROX1 is frequently overexpressed in colon cancers, where its overexpression correlates with E-cadherin downregulation." (PMID 29652830, 2018). "Prox1 was shown to mediate alterations of cell cytoskeleton, adhesiveness and cell shape as well as to induce cell migration in colon cancer cell lines." (PMID 29371975, 2017). "We have characterized the impact ERβ has on the transcriptome of colon cancer cells, and in particular, we noted a downregulation of prospero homebox 1 (PROX1) in the cancer cell line SW480." (PMID 27283988, 2016). "We also evaluated the ability of β-catenin to interact with the regulatory elements of PROX1, which is a known target of the Wnt/β-catenin signaling pathway, in other contexts such as colon cancer cells and neural stem cells." (PMID 27313318, 2016). "As PROX1 is known to increase invasiveness, its repression by ERβ and miR-205 should be important in relation to colon tumor progression and invasion." (PMID 27283988, 2016). "In different human colon cancer cell lines, we observed a clear inverse expression of miR-205 and PROX1 protein." (PMID 27283988, 2016). "Recently, it has been found that PKCΒ hypermethylation is dependent on transcription factor PROX1 (prospero-related homeobox 1) high expression levels in colon cancer." (PMID 25366420, 2015). "In a colon cancer study, miR-9 expression was activated by PROX1 (Prospero homeobox 1) and also leads to downregulation of E cadherin." (PMID 25614041, 2015). "Prox1 has been reported to promote tumor progression by influencing cancer cell migration and invasion in colon cancer and kaposiform hemangioendothelioma, and our results are consistent with these findings." (PMID 24647631, 2014). "Prox1 is a nuclear transcription factor and is activated in colon cancer, WHO grade II gliomas, and many vascular endothelial tumors." (PMID 24647631, 2014). "The 5-year CCSS of the colon cancer patients with low PROX1 expression was 62% (95% CI, 55.2–68.9%), as compared with 47% for those with high staining intensity (95% CI, 35.3–59.0%)." (PMID 21970873, 2011). "The 5-year CCSS among colon cancer patients with very high (score 4; n=11) PROX1 expression was only 24%, suggesting that increased tumour cell expression of PROX1 is associated with worse outcome of the colon cancer patients." (PMID 21970873, 2011). "Expression of ERβ changes micro‐RNAs (miRs) pool in colon cancer cells, which in turn, could downregulate the expression of Myc and Prospero homeobox protein‐1 (PROX1) oncogenes." (PMID 36207986, 2023). "AXIN2, LEF1, TCF7, and PROX1 were highly expressed in colon cancer compared with control samples." (PMID 37584250, 2023). "Recently, more and more studies have found that the abnormally high expression of PROX1 is related to many systemic malignant diseases such as neuroblastoma, colon cancer, kidney cancer, gastric cancer, esophageal squamous cell carcinoma and hepatocellular carcinoma." (PMID 35342346, 2022). "As a downstream effector of TCF/β-catenin signaling in colorectal cancer, loss of PROX1 does not directly affect cell proliferation, but it rather shifts the transcriptional phenotype of colon cancer cells towards more slowly growing adherent cells." (PMID 28854215, 2017). "The Wnt/β-catenin pathway regulates PROX1 expression in colon cancer cells and neural stem cells." (PMID 27313318, 2016). "PROX1 also promotes epithelial-to-mesenchymal transition (EMT) in colon cancer cells." (PMID 27283988, 2016). "However, recent reports have demonstrated that upregulation of Prox1 is a predictor of poor outcome in colon cancer, glioma, and many vascular endothelial tumors." (PMID 24647631, 2014).
colon cancer (continued). "In accord with our findings, Lu and colleagues found that forced expression of PROX1 in colon cancer cells also down-regulated E-cadherin expression and attenuated cell adhesion; conversely, knockdown of PROX1 restored E-cadherin expression and reduced invasiveness." (PMID 24797520, 2014). "Some insights may be obtained from interesting findings that PROX1 was shown to increase the invasion of endothelial tumor cells and that PROX1 promotes the transition from benign to highly dysplastic phenotype in colon cancer." (PMID 20730087, 2010). "The potential interplay between PROX1 and ferroptosis in colon cancer remains unclear." (PMID 36815375, 2023). "Moreover, female colon cancer patients with high PROX1 expression exhibited an unfavorable CSS." (PMID 35885529, 2022). "Therefore, as ERβ and miR-205 repress PROX1, we evaluated whether they impacted expression of different mesenchymal and adhesion markers in colon cancer cells." (PMID 27283988, 2016). "In a study focused on colon cancer, researchers found that PROX1 (Prospero homeobox 1) activated the expression of miR-9, subsequently leading to the downregulation of E-cadherin." (PMID 40761244, 2025). "In colorectal cancer, PROX1 has been identified as a downstream target of the TCF/beta-catenin signaling pathway, and its lower expression in colon cancer cells was connected with estrogen receptor beta signaling." (PMID 32370142, 2020). "Glioma, esophageal carcinoma and colon cancer display high PROX1 levels indicative of an oncogenic role, while in hepatocellular carcinoma (HCC) PROX1 expression is reduced, suggesting a tumour-suppressive role." (PMID 29934628, 2018). "Our previous studies showed that expression of ERβ resulted in increased miR-205 levels, and decreased PROX1 levels, in SW480 colon cancer cells." (PMID 27283988, 2016). "PROX1 promotes tumor progression in APCMin/+ mice, and its knockdown in SW480 colon cancer cells results in increased transcription of genes related to cell adhesion." (PMID 27283988, 2016). "Colon cancer has also been shown to contain endothelial cells which co-express both CD34 and Prox-1, which may suggest that the co-expression of these lineage markers is a result of tumorigenesis in endothelial tumors." (PMID 37046832, 2023). "Interestingly, PROX1 inhibits the expression of E-cadherin, in this way promoting epithelial-mesenchymal transformation (EMT) and, thus, colon cancer progression and invasiveness." (PMID 35885529, 2022). "They showed that this treatment strategy caused cell cycle arrest at the G1 phase in female (HT-29) and male (SW480) colon cancer cells by decreasing the expression of MYC, MYB, and the PROX1 oncogenes and increasing the expression of the p21Waf1/Cip1 and p27Kip1 cell cycle inhibitors." (PMID 36412903, 2022). "While PROX1 does not appear to be responsible for the initiation of colon tumor cell growth, it promotes progression from a benign to a malignant phenotype." (PMID 32370142, 2020). "This function of miR-205 is, however, not dependent on its ability to repress PROX1, as PROX1 does not directly affect the proliferation of colon cancer cells." (PMID 27283988, 2016).